CSK (C-terminal Src kinase)
Description:
Non-receptor tyrosine-protein kinase that plays an important role in the regulation of cell growth, differentiation, migration and immune response. Phosphorylates tyrosine residues located in the C-terminal tails of Src-family kinases (SFKs) including LCK, SRC, HCK, FYN, LYN, CSK or YES1. Upon tail phosphorylation, Src-family members engage in intramolecular interactions between the phosphotyrosine tail and the SH2 domain that result in an inactive conformation. To inhibit SFKs, CSK is recruited to the plasma membrane via binding to transmembrane proteins or adapter proteins located near the plasma membrane. Suppresses signaling by various surface receptors, including T-cell receptor (TCR) and B-cell receptor (BCR) by phosphorylating and maintaining inactive several positive effectors such as FYN or LCK. May act as a negative regulator of EGFR and STAT3 signaling pathways.
Tractability: Small molecule: a structure with a bound ligand is known; a high-quality ligand is known; it has a high-quality binding pocket; it belongs to a druggable protein family. Antibody: its Gene Ontology location is reachable by antibodies, with high confidence; UniProt places it where antibodies can reach, with medium confidence. PROTAC: it is named in the literature on targeted protein degradation; ubiquitination databases record sites on it; its protein half-life has been measured; a small molecule that binds it is known.
Target class: Protein Kinase; Tyrosine protein kinase Csk family; TK protein kinase group; Enzyme; Kinase
Gene: Protein-coding gene on chromosome 15 (74,782,055 to 74,803,198, forward strand). Ensembl gene ENSG00000103653.
Subcellular location: Cytoplasm; Cell membrane
Subcellular location (Human Protein Atlas): Cytosol; Vesicles
Pathways (Reactome):
Disease: Paradoxical activation of RAF signaling by kinase inactive BRAF; Signaling by BRAF and RAF1 fusions; Signaling by RAF1 mutants; Signaling by high-kinase activity BRAF mutants; Signaling by moderate kinase activity BRAF mutants; Signaling downstream of RAS mutants
Signal Transduction: GAB1 signalosome; Integrin signaling; MAP2K and MAPK activation; RHOH GTPase cycle
Immune System: Co-inhibition by PD-1; Negative regulation of FLT3; Phosphorylation of CD3 and TCR zeta chains
Gene Ontology:
Molecular function: identical protein binding; protein binding; protein kinase A catalytic subunit binding; protein tyrosine kinase activity; non-membrane spanning protein tyrosine kinase activity; ATP binding; proline-rich region binding; protein kinase activity; protein phosphatase binding; protein tyrosine kinase binding; transferase activity
Biological process: negative regulation of Golgi to plasma membrane protein transport; adherens junction organization; protein phosphorylation; regulation of Fc receptor mediated stimulatory signaling pathway; T cell costimulation; T cell receptor signaling pathway; cellular response to peptide hormone stimulus; intracellular signal transduction; negative regulation of bone resorption; negative regulation of cell population proliferation; negative regulation of ERK1 and ERK2 cascade; negative regulation of interleukin-6 production; negative regulation of low-density lipoprotein particle clearance; negative regulation of phagocytosis; negative regulation of T cell activation; negative regulation of T cell receptor signaling pathway; oligodendrocyte differentiation; regulation of immune response; regulation of multicellular organismal process
Cellular component: cytosol; extracellular exosome; plasma membrane; cytoplasm; cell-cell junction
Genetic constraint (gnomAD): Loss-of-function variants: 7 observed, 59.17 expected, observed/expected ratio (o/e) 0.12, 90% interval 0.066 to 0.22. The upper end of that interval is the gene's LOEUF score, 0.22, which puts it in group 1 of 6, group 1 being the genes least tolerant of losing a copy. Missense variants: 294 observed, 617.81 expected, observed/expected ratio (o/e) 0.48, 90% interval 0.43 to 0.52. Synonymous variants: 237 observed, 247.52 expected, observed/expected ratio (o/e) 0.96, 90% interval 0.86 to 1.07.
Homologues: Orthologues: chimpanzee CSK (100% identical), macaque CSK (99% identical), dog CSK (99% identical), guinea pig CSK (99% identical), mouse Csk (99% identical), rat Csk (98% identical), pig CSK (98% identical), zebrafish csk (86% identical), tropical clawed frog csk (78% identical). Paralogues in human: MATK (53% identical), ABL2 (42% identical), ABL1 (41% identical), SRC (40% identical), LYN (38% identical), LCK (38% identical), FGR (38% identical), TEC (38% identical), FYN (37% identical), YES1 (37% identical), FRK (37% identical), HCK (37% identical), and 20 more.
Diseases named in the same sentence as CSK in open-access papers:
CSK is named in the same sentence as 79 diseases in open-access papers, as found by Europe PMC text mining. Sharing a sentence is not in itself a finding about the gene and the disease. The quoted sentences say what the papers report.
breast carcinoma (28 papers, 2010 to 2025). "CSK encodes a C-terminal Src kinase that has previously been found to act as a tumor suppressor in both breast cancer and prostate cancer." (PMID 32369930, 2020). "Our finding that CSK is required for this fulvestrant action provides additional insights into how the kinase/phosphatase-mediated intracellular signaling network in human breast cancer cells is closely linked to antiestrogen sensitivity." (PMID 23593342, 2013). "Overall, we found 5 proteins (PEX14, CTSF, SNUPN, CSK, PARK7) with strong causal links to breast cancer." (PMID 38304232, 2023). "In ER-positive breast cancer, CSK (OR = 0.955, p = 0.038) and CTSF (OR = 1.125, p < 0.001) maintained the same causal trends as observed in breast cancer." (PMID 38304232, 2023). "Among the 5 plasma proteins, SNUPN, CSK, and PARK7 emerged as “Strong” negatively causative associated proteins, indicating a protective effect against breast cancer development." (PMID 38304232, 2023). "Recent study indicates that CSK maintains negative regulation of Src through Tyr527 phosphorylation, inhibiting breast cancer cells growth and spread." (PMID 38304232, 2023). "In TCGA data provided by the Cancer Genome Atlas, we find HCK, LYN, LCK, and CSK are higher in basal-like breast cancer subtypes." (PMID 28771473, 2017). "Our present study provides important insights into the molecular mechanisms of the cytocidal action of fulvestrant in human breast cancer cells, providing evidence of requirement of CSK." (PMID 23593342, 2013). "Alterations in CSK may provide another mechanism for disrupting the PRC2 complex in MPNSTs, similar to findings in breast cancer where CSK loss alters the expression of PRC2 subunits EZH2 and SUZ12." (PMID 41463204, 2025). "Enrichment difference analysis of the genes showing changes after OHT treatment revealed known breast cancer oncogenes such as HDAC3, UBE2C and CPSF7 among the depleted genes and reported breast cancer suppressors such as CSK, SPRED2 and TSC2 among the enriched genes." (PMID 38914552, 2024). "RNAi knockdown of CSK caused specific resistance to fulvestrant without affecting MCF-7 cell sensitivities to tamoxifen or paclitaxel, suggesting possible importance of CSK for better understanding of the mechanisms of the cytocidal action of fulvestrant in human breast cancer cells." (PMID 23593342, 2013). "Furthermore, HCK overexpression may be caused by suppression of C-terminal Src kinase and Cbp/PAG regulation pathway, such as in hepatocellular carcinoma 44, and by tyrosine phosphatases, such as in breast cancer." (PMID 33162805, 2020). "Some of the top hits identified by our screen, including PTEN, CSK, NF1, and TSC1/2 had previously been identified by a CRISPR-Cas9 screen that was performed with the ERα+ breast cancer cell lines MCF7 and T47D." (PMID 37172090, 2023). "Screens with the tamoxifen-sensitive breast cancer cell lines MCF7 and T47D identified gene deletions, such as that of CSK, mediating estrogen-independent growth." (PMID 37172090, 2023). "The remaining 3 proteins, SNUPN (OR = 0.905, p < 0.001), CSK (OR = 0.962, p = 0.038), and PARK7 (OR = 0.954, p < 0.001), all exhibited negative causations with breast cancer." (PMID 38304232, 2023). "Additionally, CSK and CTSF followed the same trends with the findings from breast cancer." (PMID 38304232, 2023).
Hypertension (8 papers, 2013 to 2025). The presence of chronic increased pressure in the systemic arterial system. "Our results proposed that there are interaction effects of CSK and urinary sodium-potassium ratio on the risk of hypertension." (PMID 28273873, 2017). "Out of 22 tagging SNPs, two SNPs (c-src tyrosine kinase (CSK) rs1378942, CSK-micro RNA 4513 (MIR4513) rs3784789) had significant interaction effects with 24 h estimated urinary factors on the risk of hypertension." (PMID 28273873, 2017). "A gene CSK in which SNP rs1378942 is located has been reported as a hypertension susceptibility gene in the Korean population and also in East Asians." (PMID 24565370, 2013). "A meta-analysis with two Korean cohorts (The KoGES_Ansan and Ansung Study and The KoGES_health examinees (HEXA) study) found that CSK increases the risk of hypertension in the group with major allele homozygotes of CSK, which is the same as the group with the risk allele." (PMID 28273873, 2017). "Aberrant CSK and/or SFK activity can be associated with a large number of diseases, such as cancer, autoimmune, autoinflammatory and neurologic diseases, hypertension and HIV/AIDS." (PMID 36578781, 2022). "All in all, the increase in sodium levels and thus plasma volume on the one hand, and the disturbing influence of Ang II and aldosterone on VSMCs on the other hand, that are both mediated through a decrease in CSK activity, promote hypertension." (PMID 36578781, 2022). "CSK has been shown to engage in blood pressure regulation and CSK depletion has been identified as a possible trigger for hypertension." (PMID 36578781, 2022). "A total of 178 SNPs were significantly associated with hypertension in GWAS, and 22 SNPs for 21 gene symbols including ATP2B1 and CSK, which were frequently investigated with blood pressure and hypertension, were selected as tagging SNPs." (PMID 28273873, 2017). "The present study results indicated that the mutant alleles of CSK rs1378942 and CSK-MIR4513 rs3784789 had the strongest protective effects against hypertension in the middle group of 24 h estimated urinary sodium-potassium excretion ratio." (PMID 28273873, 2017). "The prominent finding of this study is the protective effect of minor allele homozygotes of CSK rs1378942 and CSK-MIR4513 rs3784789 on the risk of hypertension in the middle group for the 24HUNa-K ratio." (PMID 28273873, 2017). "In conclusion, the present study results indicate the protective effects of minor allele homozygotes of CSK rs1378942 and CSK-MIR4513 rs3784789 on hypertension in the middle group for the 24HUNa-K ratio." (PMID 28273873, 2017). "This review describes apoptosis regulation by CSK, CSK inhibition of the SFKs and further explores the clinical relevance of CSK in important pathologies, such as cancer, autoimmune, autoinflammatory, neurologic diseases, hypertension and HIV/AIDS." (PMID 36578781, 2022). "A cross-sectional study in Korea indicated that the mutant alleles of CSK rs1378942 and CSK-MIR4513 rs3784789 had the strongest protective effects against hypertension in the subjects in the middle group of the 24-h estimated urinary sodium-potassium excretion ratio." (PMID 30857519, 2019). "In this Review, we are focusing on revealing the apoptosis regulation mechanisms by CSK, CSK inhibition of the SFKs, while further exploring the clinical relevance of CSK in important pathologies, such as cancer, autoimmune, autoinflammatory, neurologic diseases, hypertension and HIV/AIDS." (PMID 36578781, 2022). "The strongest protective effects of variants of CSK rs1378942 (p-interaction = 0.013; OR = 0.08; 95% CIs = 0.01–0.67) and CSK-MIR4513 rs3784789 (p-interaction = 0.027; OR = 0.08; 95% CIs = 0.01–0.72) on the risk of hypertension was found in the second tertile for the 24HUNa-K ratio." (PMID 28273873, 2017).
Hypertension (continued). "Ibrutinib-specific off-targets LCK, JAK3, and FLT3 were predicted to trigger inflammation processes related to hypertension; ERBB2, BLK, SRC, and CSK were predicted to trigger oxidative stress and endothelial dysfunction; and CSK were predicted to trigger the RAAS overactivation." (PMID 40744952, 2025).
colon cancer (7 papers, 2016 to 2025). "CSK overexpression actually causes inhibition of in vivo tumor growth and metastasis in colon cancer cell lines." (PMID 27765068, 2016). "The chemical protective effect of isorhamnetin on colon cancer is related to its anti-inflammatory activity, inhibition of carcinogenic Src activity, and corresponding loss of nuclear β-catenin, which depend on the expression of C-terminal Src kinase (CSK)." (PMID 40868987, 2025). "In HT-29 colon cancer cells, isorhamnetin’s chemoprotective properties against colon cancer are attributed to its anti-inflammatory activity as well as its inhibition of Src-mediated carcinogenesis, leading to the subsequent loss of nuclear beta catenin that relies on CSK expression." (PMID 39045282, 2024). "For example, SFK-driven colon cancer cell invasion is induced by dysregulation of CSK membrane localisation." (PMID 37519303, 2023). "In colon cancer cells, regulation of Src signaling is highly perturbed due to defects in the regulation of its catalytic activity due to CSK inactivation, which mediates Src-Tyr530 phosphorylation." (PMID 34999732, 2022). "On the contrary, mis-localization of CSK could activate SFKs and lead to increased oncogenicity in colon cancer cells." (PMID 37397251, 2023). "This suggests that levels of CSK are uncoupled from SFK activity in colon cancer cells." (PMID 37397251, 2023). "For example, CSK defines integrin-mediated cell adhesion and migration in human colon cancer cells." (PMID 37519303, 2023). "Furthermore, overexpression of CSK in human colon cancer cells (adenocarcinoma) inhibits tumour growth." (PMID 37519303, 2023). "In colon cancer cells, CSK expression levels were inconsistent with SFK activity; nevertheless, CSK translocation to the plasma membrane was impaired by downregulation of its scaffolding protein CBP." (PMID 37519303, 2023). "Further study shows that downregulation of CSK either by a small molecule inhibitor or by shRNA knockdown does not affect SFK kinase activity or oncogenic activity in colon cancer cells." (PMID 37397251, 2023). "Similarly, there is no significant change in CSK expression between cancerous colon tissues/cell lines and normal colon tissues/cell lines although Src is activated in the colon cancer samples with reduced phosphorylation at Src Y530." (PMID 37397251, 2023). "Interestingly, CSK expression was inversely correlated with PRL-3 expression, consistent in previous reports that found PRL-3 down-regulates CSK expression in human embryonic kidney cells and colon cancer cells." (PMID 32001668, 2020). "However, change of CSK protein levels has not been found in many cancers, such as colon cancer." (PMID 37397251, 2023).
prostate carcinoma (7 papers, 2013 to 2024). A carcinoma that arises from epithelial cells of the prostate gland. "The effects of CSK knockdown on androgen-independent proliferation were corroborated in another androgen responsive prostate cancer cell line, LAPC4." (PMID 26091350, 2015). "Staining of the prostate cancer progression panel with this validated antibody revealed a significant decrease in average CSK reactivity in metastatic prostate cancer and CRPCs relative to primary prostate cancers." (PMID 26091350, 2015). "Performing a functional genomics screen, we found that downregulation of SRC inhibitory kinase CSK is sufficient to overcome growth arrest induced by depriving human prostate cancer cells of androgen." (PMID 26091350, 2015). "Taken together, these findings demonstrate that downregulation of CSK is sufficient to confer a castration resistant phenotype to androgen responsive prostate cancer cells in vivo." (PMID 26091350, 2015). "CSK has been found highly expressed in normal organs, while its reduced expression and concomitant increased c-Src activity were reported in many cancer types, including hepatocellular carcinoma and prostate cancer." (PMID 27765068, 2016). "On the other hand, CSK can interact with the known drug Dasatinib, and BRDT can interact with Birabresib, both drugs went into clinical trials for castration-resistant prostate cancer revealing their potential as therapeutic targets." (PMID 38983753, 2024). "Among these targets, five of them (A2AR/ADORA2A, CSK, CYP24A1, BRDT, and BRAF) have been suggested in recent scientific papers to be related to prostate cancer and all can interact with ligands with known therapeutic advantages against advanced prostate cancer." (PMID 38983753, 2024).
hepatocellular carcinoma (6 papers, 2015 to 2024). A malignant tumor that arises from hepatocytes. "Reportedly, the CSK level was reduced in human hepatocellular carcinoma, suggesting that CSK has this antitumor effect." (PMID 38667199, 2024). "Together, the results suggest CSK as a tumor suppressor, a role that has previously been inferred from the observation of CSK downregulation in hepatocellular carcinoma." (PMID 26091350, 2015).
atrial fibrillation (5 papers, 2024 to 2025). A disorder characterized by an electrocardiographic finding of a supraventricular arrhythmia characterized by the replacement of consistent P waves by rapid oscillations or fibrillatory waves that vary in size, shape and timing and are accompanied by an irregular ventricular response. "Acalabrutinib’s enhanced specificity for BTK and/or less inhibition of C-terminal Src kinase may cause lower off-target effects, explaining the lower incidence of atrial fibrillation in our cohort of patients." (PMID 38824606, 2024). "IHMT-15130 shows selectivity for CSK kinase, and its targeting of CSK may lead to severe atrial fibrillation and bleeding." (PMID 41567642, 2025). "In addition, it is hypothesized that atrial fibrillation is related to inhibition of Fyn, mitogen-activated protein/extracellular signal regulated protein kinase 5, or C-terminal Src kinase (CSK)." (PMID 38829647, 2024).
autoimmune disease (5 papers, 2015 to 2024). A disorder resulting from loss of function or tissue destruction of an organ or multiple organs, arising from humoral or cellular immune responses of the individual to their own tissue constituents. "Taken together, the results in terms of PTPN22/CSK association with autoimmune diseases support the notion that different pathogenic mechanisms are involved in the development of polygenic disorders." (PMID 26458874, 2015). "PTPN22/CSK pathway has been postulated as a potential common genetic factor shared for different autoimmune disorders." (PMID 26458874, 2015). "PTPN22 has four proline-rich motifs (P1-P4) at the C-terminus, and the P1 motif interacts with the SH3 domain of CSK; rs2476601 (GRCh38 NC_000001.10:g.114377568A>G) is located in the P1 motif of PTPN22; rs2476601 is associated with more than ten autoimmune diseases, including T1D." (PMID 37240014, 2023). "CSK inactivates the sarcoma (Src) family kinases which otherwise would lead to T-Cell antigen specific response by phosphorylating zeta chain T-cell receptor (TCR), which has been found downregulated for different cancer types, autoimmune disease and chronic inflammation." (PMID 28725034, 2017).